EGFR (epidermal growth factor receptor)
Diseases named in the same sentence as EGFR in open-access papers (continued):
Sharing a sentence is not in itself a finding about the gene and the disease.
tumor (continued). "Consistent with the dual-flank tumor xenograft system, the TGI activity mediated by the monospecific DuetMab variants was inversely proportional to the reduced affinity to EGFR." (PMID 28067257, 2017). "In vitro studies suggest that IGFBP-3, which potentiates EGFR signaling via activation of SphK1, is a driver of proliferation in these tumors and its measurement in tumor tissue should be evaluated as a potential biomarker of drug combination efficacy." (PMID 28778177, 2017). "Immuno-PET imaging represented the extent of target expression and RIT showed marked inhibition of tumor growth in EGFR expressing ESCC." (PMID 29190900, 2017). "The prognostic values of EGFR expression were evaluated in the subgroup analysis of tumor location (right- vs. left-sided colon)." (PMID 29383110, 2017). "Our aim in this study was therefore to determine the clonality of EGFR from the primary tumor, metastatic lesion, recurrence and SPT lesions in OSCCs." (PMID 28854970, 2017). "HSC3 cells produce tumors in athymic nude mice, and the growth of HSC3 tumor xenografts is inhibited by blocking EGFR activity, indicating that these tumors are EGFR-dependent." (PMID 29268862, 2017). "ND-PTX-Cet markedly decreased tumor growth in the human EGFR-expressed CRC xenograft tumors of nude mice." (PMID 28852020, 2017). "Irradiation of FaDu cell xenografts showed enhancement of tumor cell population with upregulated EGFR, while the combination of cetuximab and IR reduced tumor cells and improved local control." (PMID 28423495, 2017). "EGFR and KRAS mutation tests are often carried out from formalin-fixed paraffin embedded (FFPE) tumor tissue samples." (PMID 28430611, 2017). "It is therefore worthwhile to investigate tumor cells with increased EGFR amplification because the number of EGFR copies plays an important role in metastasis, recurrence or development of secondary primary tumors (SPTs)." (PMID 28854970, 2017). "Subcutaneous (s.q.)grafting of HSC3/EGFR-GFP cells into the flanks of athymic nude mice led to tumor formation." (PMID 29268862, 2017). "At the same time, the correlation between EGFR expression level and tumor size (mean=39mm, n=40) was analyzed by the chi-square test (P=0.02), the result indicated that the expression of EGFR was significantly correlated with CRC cell growth." (PMID 29069815, 2017). "We compared the relative density of the protein band for total EGFR, p-EGFR, total Akt, and p-Akt to those of internal control bands from the same mouse's tumor tissue lysate." (PMID 29228651, 2017). "A recent study shows that tumor cells overexpressing EGFR are more sensitive to anti-IAPs therapy, suggesting a potential relationship between XIAP and EGFR in cancer cells." (PMID 28057023, 2017). "Both these cell lines express wild-type EGFR, and their tumor xenografts are shown to be growth-dependent on the EGFR activity." (PMID 29268862, 2017). "EGFR is known to activate a cascade of multiple signaling pathways that facilitate tumor growth process." (PMID 28938543, 2017). "Primarily, it should be clarified how representative KRAS genotyping in cfDNA is in comparison to tumor tissue assessment, which is the gold standard in deciding regarding anti-EGFR treatment." (PMID 28328955, 2017). "Phosphorylation of EGFR and its downstream signalling were actually inhibited by brigatinib in tumour samples obtained from mice." (PMID 28287083, 2017). "Osimertinib, a 3rd generation EGFR-TKI, is the appropriate second-line drug after acquisition of resistance to gefitinib, erlotinib, or afatinib if a rebiopsied resistant tumor proves the presence of an EGFR T790M secondary mutation." (PMID 29119113, 2017). "Large-area montage images of the tumor section demonstrate a predominantly plasma membrane localization for EGFR-GFP." (PMID 29268862, 2017). "Consistently, the aptamer inhibited EGFR-integrin αvβ3 interaction, VM and tumor growth in a xenograft TNBC model." (PMID 28425453, 2017).
tumor (continued). "Although EGFR is well known to be upregulated in tumour tissues, few studies have been focused on circulatory EGFR delivered by exosomes." (PMID 28393839, 2017). "The aim of the present study was to evaluate the clinical significance of serum EGFR (sEGFR) in relation to circulating tumor cells (CTCs) in metastatic breast cancer." (PMID 29229933, 2017). "In vivo, dual inhibition of EGFR and c-Met retarded tumor growth, decreased the proliferative index, and enhanced apoptosis compared to either single agent." (PMID 28441771, 2017). "Two commonly expressed tumor antigens in GBM include the epidermal growth factor receptor mutant (EGFRvIII) and the interleukin-13 receptor alpha 2 (IL-13Rα2), which are potential targets for the treatment of GBM2,3." (PMID 29203859, 2017). "The expression of HB-EGF, epiregulin, and phosphorylated EGFR (1068 and 1173) were undetectable in tumour sections in this study." (PMID 28032593, 2017). "Mutations in the RTK genes involving EGFR, ERBB2, ERBB4, FLT1 and EPHA/B, were identified in 5/7 (71%) of the H3/IDH1 wildtype tumor pairs." (PMID 29084603, 2017). "Responses were seen in 5 patients, 2 with EGFR mutant tumours, 1 with EGFR wild type but 2 had insufficient tissue for genotyping." (PMID 29050231, 2017). "We found that both lnc-EGFR and EGFR were highly upregulated in tumour-infiltrating T cells compared to the peripheral blood T cells from HCC patients and healthy controls." (PMID 28541302, 2017). "Among DLM patients, OS was similar between the EGFR-mutant and wild-type EGFR tumor subgroups (11.9 vs. 7.7 months, p = 0.155)." (PMID 28591157, 2017). "The percentage of EGFR expression on tumor cell lines A549, HepG2, SW116 calculated from the corresponding dot plot was 55.6%, 79.6% and 97.1%, respectively, but SW620 was only 4.45%." (PMID 28445134, 2017). "The EGFR tyrosine kinase inhibitors (EGFR-TKIs) have become an important focus for tumor-related drug development, such as small-molecule targeted drugs, monoclonal antibodies and cancer vaccines." (PMID 28181832, 2017). "Future experiments should look at the vascularization inside, around, and far beyond the tumor boundary, for example, with dynamic contrast enhanced MRI and with epidermal growth factor receptor staining." (PMID 29362558, 2017). "Combined inhibition of EGFR and mTOR exhibited synergistic cytotoxicity in several human tumor cell lines." (PMID 29234489, 2017). "Analyses of in vitro data showed that cRGD-siEGFR silenced EGFR expression effectively, with high tumor targeting ability." (PMID 28181832, 2017). "To date, this gradient had been largely reported in CRC, with higher expression of EGFR in the front of tumor invasion vs the surface of the tumor, and in metastasis localizations compared to the primary tumor." (PMID 28157706, 2017). "It was shown also that when tumor cells with high levels of EGFR were injected into mice and treated with EGFR inhibitors, gene expression and DNA copy number of endogenous FAM83A increase, making surviving tumor cells resistant to therapy." (PMID 28078827, 2017). "Spatio-temporal analyses in vitro revealed that perturbation of signaling pathways relevant for the initiation and maintenance of a migration front phenotype (e.g. the EGF/EGFR pathway) only partly reduced tumor cell motility." (PMID 28649432, 2017). "The detection of tumour heterogeneity and resistance mechanisms after EGFR TKI therapy largely relied on tumor biopsies." (PMID 29088904, 2017). "Preclinical studies confirmed osimertinib antitumor activity and reduced activity against wild-type EGFR in cell lines and tumor xenograft and transgenic mouse models harboring EGFRm+ and EGFR T790M." (PMID 28969097, 2017). "The dimerization of EGFR and HER2 is associated with poor prognosis such as induction of tumor growth and cell invasion compared to when EGFR remains as a homodimer." (PMID 28881584, 2017).
tumor (continued). "Theliatinib exhibited strong antitumor activity in PDECX models with high EGFR expression, including remarkable tumor regression in two PDECX models with both EGFR gene amplification and protein overexpression." (PMID 28881608, 2017). "The PI3K/AKT/mTOR pathway promotes cell growth and proliferation in many tumor types and is the most important downstream signaling pathway mediated by EGFR in NB cells." (PMID 27902463, 2017). "The intraperitoneal tumor tissues from the B6 mice that were treated with SsaI showed decreased expression of ST3GalI and EGFR compared to the control mice based on DuoLink in situ double staining." (PMID 28423672, 2017). "MiR-193a-3p, delivered to MPM tumours in nanocells with EGFR antibodies, inhibited xenograft growth and induced tumour cell apoptosis in mice." (PMID 29100460, 2017). "Among the pairs of tissues, we found that the level of EGFR expression was upregulated in tumor tissues, when compared with their non-tumor tissues." (PMID 28825720, 2017). "Here, we retrospectively analyzed the tumor proportion score (TPS) for PD-L1 expression and CD8+ TILs in paired tumor tissues from NSCLC patients harboring activating EGFR mutants before and after developing acquired resistance to EGFR-TKIs." (PMID 29296194, 2017). "Our results reveal that sortilin regulates EGFR by controlling its internalization from the plasma membrane, thereby limiting proliferative signaling, an essential driving force behind tumor aggressiveness." (PMID 29084952, 2017). "Most recently, several studies have demonstrated the relation between EGFR activation and dysregulated Warburg effect or aerobic glycolysis in tumor cells." (PMID 27926487, 2017). "EGFR mutations were screened in ctDNA and CTCs using the Scorpion amplification refractory mutation system (SARMS) and in tumor samples using SARMS or standard sequencing." (PMID 29312651, 2017). "Activating EGFR/AKT signaling is known to promote tumorigenesis, and EGFR signalinghas regarded as a promising target to control tumor development." (PMID 29228651, 2017). "It appears to be important to this GBM to maintain the tumor subpopulation with EGFR overexpression, manifested via DM or a mechanism of EGFR up-regulation." (PMID 29113349, 2017). "This is important in advanced NSCLC patients for whom selection for targeted therapies using EGFR-TKI is based on the presence of EGFR actionable mutations and therefore requires tumor genotyping." (PMID 28829811, 2017). "The histopathological evaluation of tumors by immunostaining, such as that revealing an increased Ki-67 index or epidermal growth factor receptor (EGFR) expression, has also been shown to reflect tumor progression and development." (PMID 28430583, 2017). "In this work, a promising anti-tumor conjugate comprising methoxy-modified EGFR siRNA and cyclic arginine-glycine-aspartic acid (cRGD) peptides, which selectively bind to αvβ3 integrins, was synthesized and examined." (PMID 28181832, 2017). "EGFR expression in the tumor tissue can be assessed by immunohistochemistry and in situ hybridization, resulting in overexpression rates in BC patients ranging from 6 to 60%, depending on the method used." (PMID 29229933, 2017). "Here, we show that lnc-epidermal growth factor receptor (EGFR) upregulation in Tregs correlates positively with the tumour size and expression of EGFR/Foxp3, but negatively with IFN-γ expression in patients and xenografted mouse models." (PMID 28541302, 2017). "Here, we utilized alive tumor tissues in ex-vivo platform termed CANscript, which preserves the native tumor heterogeneity, in order to interrogate the antitumor effects of EGFR-targeted drugs in mCRC (n = 40)." (PMID 28473715, 2017). "Compared to PBS-treated animals, JNJ-61186372-LF and EGFR-LF monovalent antibodies showed significant percent tumor growth inhibition (% TGI) of 79 and 81, respectively (each with p < 0.05)." (PMID 27786612, 2017).
tumor (continued). "Several studies performed systematic review and meta-analysis to assess the prognostic value of EGFR and KRAS mutations in tumor tissue in NSCLC patients." (PMID 28430611, 2017). "Results showed a significant downregulation of Ki67 and EGFR in the tumor tissues stably pLenti-miR-34a, accompanied by an induction of E-cadherin expression, but a decrease in the expression of N-cadherin." (PMID 28825720, 2017). "Plasma samples and tumor samples were collected from patients with acquired EGFR‐TKI resistance in Zhejiang Cancer Hospital from December 2014 to December 2015." (PMID 28000387, 2017). "Many potential targets of miR-7 were reported to participate in some important signalling of tumor progression, such as targets EGFR, IRS-1, PAK-1, RAF-1, SATB1, and so on." (PMID 28239300, 2017). "It is widely accepted that EGFR plays important roles in tumor cell proliferation, invasion, angiogenesis, metastasis and apoptosis." (PMID 28430623, 2017). "Until 2015, the epidermal growth factor receptor inhibitor cetuximab, a tumour-specific antibody, represented the only Food and Drug Administration (FDA)-approved targeted therapy for SCCHN." (PMID 28571578, 2017). "Within this network, several genes were identified namely CCND1, RELA, TP63, and EGFR as being major contributors to tumour cell proliferation, immortalization, and metastasis in oral tumourigenesis." (PMID 28384287, 2017). "The same group evaluated the relationship between tumor uptake of the EGFR-specific Nb 99mTc-7C12 and the tumor burden, as well as the possibility to monitor tumor response to erlotinib with this probe." (PMID 29163515, 2017). "In summary we report, for the first time, the capacity of the anti-EGFR mAb nimotuzumab to induce ADCC-mediated tumor cell killing and adaptive immunity through TA specific T cells." (PMID 28674498, 2017). "Monoclonal antibodies block epidermal growth factor receptor (EGFR), inhibiting signal transduction and therefore leading to reduced tumor growth." (PMID 27888811, 2017). "Further, some studies have shown the therapeutic potential of CD73 blockade for cancer therapy, and the effects of CD73 on tumor cells via the EGFR signaling pathway." (PMID 28158983, 2017). "CNG of EGFR, HER2 and HER3 was positively associated with tumor recurrence, especially EGFR in female patients." (PMID 29190914, 2017). "In some specific cases, e.g., in the post EGFR-TKI therapy samples, we expect to find tumor resistance-inducing clones containing secondary mutations after treatment." (PMID 29123093, 2017). "In the present study, we have begun to address these questions using mouse tumor xenografts of human HNSCC cells engineered using gene-editing to express GFP-tagged endogenous EGFR (EGFR-GFP)." (PMID 29268862, 2017). "The effects of cranberry feeding on EGFR signaling pathway involved in tumor development were further investigated." (PMID 29228651, 2017). "Similar to previous research, we have observed amplified EGFR in only 2 of 8 ACCs and small proportion among other tumour entities, although half of samples stained 3+ by immunohistochemistry." (PMID 28377929, 2017). "At first examination, the finding that a putative tumor suppressor (i.e. EHD3) increases the levels of an oncogene (i.e. EGFR) appears counterintuitive." (PMID 27811356, 2016). "In cohort 1 and 3, the worst prognosis was seen in patients with tumours displaying high expression of both EGFR and PODXL." (PMID 27160084, 2016). "EGFR gene amplification was more common in tumours of distal oesophagus/gastro-oesophageal junction/cardia than in those of gastric corpus (p = 0.013)." (PMID 27387915, 2016). "That study reported faster disease progression compared to the historic control, and molecular analysis of tumor specimens revealed stabilization of EGFR by this combination as a potential mechanism of tumor progression." (PMID 27612423, 2016).
tumor (continued). "This proportion was significantly higher compared to MET amplification seen in anti-EGFR naïve tumor tissue-based biopsies (p < 0.001)." (PMID 27421137, 2016). "EGFR inhibition seems to be major mechanism of platycod in D's in vivo anti‐tumour efficacy as demonstrated by in vitro cell studies." (PMID 26648178, 2016). "These ligands resulted in subsequent EGFR activation and evasion of chemotherapeutic agent-induced apoptosis in tumor cells." (PMID 26799187, 2016). "In total, 13/49, 31/49, 20/49, and 34/49 of the tumor samples stained positively for Tid1-L, EGFR, hnRNP A1, and hnRNP A2, respectively." (PMID 26919236, 2016). "Mice bearing high EGFR expressing MDA-MB-468 tumours with a mean volume of 56.5 mm3 ± 21.2 (N = 5; range 35.1–89.4 mm3) were used for in vivo tumour detection with anti-EGFR nanobody 99mTc-D10." (PMID 26912069, 2016). "We previously observed that cathepsin S (CTSS) inhibition induces tumour cell autophagy through the EGFR-mediated signalling pathway." (PMID 27387133, 2016). "We demonstrated that plasma EGFR and KRAS mutation testing using PNA-based real-time PCR methods is feasible and can be applied as an alternative to tumor genotyping when deciding upon the optimal treatment of NSCLC patients." (PMID 27519791, 2016). "Under lowoxygen tension, accumulation of elevated EGFR levels, in turn mediated by increasedHIF-2α, participates to autonomy in tumor cell growth through an autocrinesignaling mechanism." (PMID 27303300, 2016). "A panel of five human tumor cell lines differently expressing EGFR was tested for ZNF216 and EGFR expression by RT-PCR and Western blotting." (PMID 27732953, 2016). "As an example, Patient 218 progressed on EGFR TKI as tumour grew by 41% on day 86; this was mirrored by increases in miR-1246 and miR-1290 levels." (PMID 27325363, 2016). "We found that ground-glass opacity at the main tumor was significantly more common among EGFR-positive patients, compared to ALK-positive patients (p = 0.009)." (PMID 27518729, 2016). "Among the transformed groups, only iNPCs dysregulated for PI3K and MAPK signalling (Ras/EGFR/SrciNPCs and p53KD-Ras/EGFR/SrciNPCs) were able to form primary tumours when 500 cells were orthotopically injected into the murine brain." (PMID 26899176, 2016). "Multivariate analysis of the impact of adjuvant trastuzumab on RFS in the EGFR SNP T903T was still significant when adjusted for ER status, tumor grade and Age (HR = 6.51 (CI = 1.98– 21.36), p = 0.01)." (PMID 27776352, 2016). "Multivariate Cox analysis identified five significant prognostic factors, including pathology tumor stage (p = 0.0103), nodal stage (p = 0.0031), EGFR (p = 0.0161), CK5/6 (p = 0.0177), and Ki-67 (p = 0.0468)." (PMID 26930401, 2016). "Multivariate analysis reveals that the OS impact of the EGFR SNP N158N is still significant when adjusted for ER status, age and tumor grade (HR = 3.47 (CI = 1.11–10.90), p = 0.03)." (PMID 27776352, 2016). "Titrating cetuximab in cultures of A431 cells (EGFR+++, RASwt), SW480 cells (EGFR+, RASmut) and COLO320 cells (EGFR-, RASwt) demonstrated that cetuximab alone induced cytotoxicity only in EGFR+ RASwt tumor cells." (PMID 27314237, 2016). "The results from the present study, based on analyses of tumours from more than 1100 patients, demonstrate, for the first time, strong significant associations between high protein expression of PODXL and EGFR in CRC." (PMID 27160084, 2016). "Taken together, our data support cell proliferation, tumor growth and progression and treatment resistance through cell IL-17R signaling activation and probably crosslinks with other receptors such as EGFR, or IGFR." (PMID 27589729, 2016). "To minimize potential systemic toxicity, we injected the non-irradiated EGFR-CAR NK-92 cells or oHSV-1 intratumorally at day 10 post-tumor cell implantation and oHSV-1 at day 15 for the group of EGFR-CAR NK-92 combined with oHSV-1." (PMID 27050072, 2016).